HOXB6 (homeobox B6)
Description:
Sequence-specific transcription factor which is part of a developmental regulatory system that provides cells with specific positional identities on the anterior-posterior axis.
Synonyms: HOX2B; HOX2; HU-2; Hox-2.2
Tractability: No criterion of Open Targets' tractability assessment is met for any kind of drug.
Gene: Protein-coding gene on chromosome 17 (48,595,525 to 48,604,992, reverse strand). Ensembl gene ENSG00000108511.
Subcellular location: Nucleus
Subcellular location (Human Protein Atlas): Nucleoplasm; Golgi apparatus
Gene Ontology:
Molecular function: protein binding; RNA binding; sequence-specific double-stranded DNA binding; DNA-binding transcription factor activity, RNA polymerase II-specific; RNA polymerase II cis-regulatory region sequence-specific DNA binding; DNA binding; DNA-binding transcription factor activity
Biological process: anterior/posterior pattern specification; regulation of transcription by RNA polymerase II; regulation of DNA-templated transcription
Cellular component: nucleoplasm; chromatin; nucleus
Genetic constraint (gnomAD): Loss-of-function variants: 18 observed, 23.04 expected, observed/expected ratio (o/e) 0.78, 90% interval 0.54 to 1.16. The upper end of that interval is the gene's LOEUF score, 1.16, which puts it in group 5 of 6, group 1 being the genes least tolerant of losing a copy. Missense variants: 332 observed, 301.49 expected, observed/expected ratio (o/e) 1.1, 90% interval 1.01 to 1.21. Synonymous variants: 159 observed, 138.85 expected, observed/expected ratio (o/e) 1.15, 90% interval 1.01 to 1.31.
Homologues: Orthologues: chimpanzee HOXB6 (100% identical), macaque HOXB6 (99% identical), rabbit HOXB6 (99% identical), mouse Hoxb6 (98% identical), pig HOXB6 (98% identical), dog HOXB6 (97% identical), guinea pig HOXB6 (93% identical), tropical clawed frog hoxb6 (73% identical), zebrafish hoxb6a (71% identical). Paralogues in human: HOXA6 (54% identical), HOXC6 (47% identical), HOXA7 (42% identical), HOXA5 (42% identical), HOXB5 (42% identical), HOXB7 (42% identical), HOXB8 (37% identical), HOXC8 (37% identical), HOXA4 (36% identical), HOXC4 (36% identical), HOXD4 (36% identical), HOXD8 (36% identical), and 30 more.
Diseases named in the same sentence as HOXB6 in open-access papers:
HOXB6 is named in the same sentence as 36 diseases in open-access papers, as found by Europe PMC text mining. Sharing a sentence is not in itself a finding about the gene and the disease. The quoted sentences say what the papers report.
acute myeloid leukemia (3 papers, 2018 to 2025). Acute myeloid leukemia (AML) is a group of neoplasms arising from precursor cells committed to the myeloid cell-line differentiation. "The hematopoietic system showed predominant HOXB6 expression; the dysregulation of this gene has been implicated in acute myeloid leukemia through aberrant differentiation of hematopoietic stem cells." (PMID 41515917, 2025). "Homeobox B6 (HOXB6) is thought to be involved in some acute myeloid leukemia and colorectal cancer." (PMID 36532015, 2022). "Upregulation of HOXB6 is often seen in acute myeloid leukemia (AML)." (PMID 30154863, 2018).
hypospadias (3 papers, 2019 to 2023). Hypospadias is the displacement of the urethral meatus on the ventrum of the penis. "Mutation of BMP4 and BMP7—two factors that play a role in normal urethra development, along with HOXA4 and HOXB6, were identified in Chinese patients with hypospadias, but without a clear association." (PMID 37238140, 2023).
leukemia (3 papers, 2015 to 2024). A malignant (clonal) hematologic disorder, involving hematopoietic stem cells and characterized by the presence of primitive or atypical myeloid or lymphoid cells in the bone marrow and the blood. "Since it is well known that MEIS1 and HOXB6 synergistically cooperate in leukemia induction, the detection of MEIS1/HOXB6 combination among the leukemic mice further validates the usefulness of the current model system." (PMID 26606454, 2015). "Notably, several essential genes involved in HSC self-renewal, metabolism, and leukemia development were increased, including GATA2, MSI2, MYCN, CD44, GAS2, HOXB4, and HOXB6." (PMID 38216972, 2024). "Although the CLDN1 band is present in addition to HOXB6, the role of CLDN1 in leukemia initiation is not clear and needs further investigation." (PMID 26606454, 2015).
colon cancer (2 papers, 2015 to 2025). "For instance, HOXB6, HOXB8 and HOXC9 are dysregulated at various stages of colon cancer development." (PMID 25875824, 2015).
colorectal cancer (2 papers, 2021 to 2022). A primary or metastatic malignant neoplasm that affects the colon or rectum. "Genes upregulated in KRAS‐mt tumors included HOXB6 and HOXB8, two homeobox genes that have been previously reported to be dysregulated in colorectal cancer." (PMID 33817986, 2021).
endometrial cancer (2 papers, 2019). Primary or metastatic malignant neoplasm involving the endometrium (mucous membrane that lines the endometrial cavity). "Also, poor prognosis of patients with endometrial cancer is associated with higher levels of HOXA4, HOX5, HOXA6, HOXA7, and HOXB9 expression, whereas favorable prognosis of patients with endometrial cancer is associated with higher levels of HOXB5 and HOXB6 expression." (PMID 30866492, 2019). "Six HiChIP target genes (BRAP, RASGRP1, HOXB1, HOXB6, HOXB7 and HOXB8) were enriched for miRNA targets of MIR196A1, itself a HiChIP target gene, providing evidence to link these genes together in a potential network that may mediate the effects of endometrial cancer risk variation." (PMID 31561579, 2019).
mediastinal tumours (2 papers, 2024 to 2025). "HN-PG and the suspected non-chromaffin mediastinal tumours had low expression of the chromaffin cell marker CARTPT24, neural transcriptional regulators (TFAP2B, TOX3, GATA3, POU4F, NEUROG2, PAX2), HOX genes (HOXA1-10, HOXB4, HOXB6-9, HOXC4-HOXC13), and the long non-coding RNA HOTAIR." (PMID 40097403, 2025). "HN-PG and the suspected non-chromaffin mediastinal tumours had low expression of the chromaffin cell marker CARTP24, neural transcriptional regulators (TFAP2B, TOX3, GATA3, POU4F, NEUROG2, PAX2), HOX genes (HOXA1–10, HOXB4, HOXB6–9, HOXC4-HOXC13), and the long non-coding RNA HOTAIR." (PMID 38978571, 2024).
Alzheimer disease (1 paper, 2020). A progressive, neurodegenerative disease characterized by loss of function and death of nerve cells in several areas of the brain leading to loss of cognitive function such as memory and language. "We identified significant differentially methylated regions, including 12 adjacent hypermethylated probes in the HOXB6 gene in Alzheimer's disease, which we validated using pyrosequencing." (PMID 32745807, 2020).
Arboleda-Tham Syndrome (1 paper, 2022). "The second overlaps part of HOXB5 and HOXB6 and is also hypomethylated in Arboleda-Tham Syndrome patients." (PMID 36064314, 2022).
bladder cancer (1 paper, 2020). "Among these identified genes, 5 genes (CALD1, HOXB3, HOXB6, MOGAT2, and TNC) have been reported to be associated with the development or prognosis of bladder cancer, indicating that the results in our study are consistent with previous publications in bladder cancer." (PMID 33204728, 2020).
cognitive decline (1 paper, 2021). "In the present study, the hypermethylation of probes in the DMRs annotated to HOXB6 was associated with faster rate of cognitive decline, whereas the hypermethylation of probes in the DMRs annotated to HOXB9 was associated with slower rate of cognitive decline." (PMID 34654479, 2021).
endometriosis (1 paper, 2022). The growth of functional endometrial tissue in anatomic sites outside the uterine body. "Given reported researches on the HOXB family members of the immune regulation, it should be possible to explore the HOXB6 in endometriosis." (PMID 36532015, 2022). "Two of them, KLF2 and HOXB6, are critical molecules in the gene interaction network of endometriosis." (PMID 36532015, 2022). "Besides, SVM-RFE and random forest algorithms identified that KLF2 and HOXB6 were the coincident genes, suggesting dominant contribution to endometriosis." (PMID 36532015, 2022). "In addition, three modules were established through Metascape, and KLF2 and HOXB6 genes were again present in two modules, implying important biomarkers in endometriosis." (PMID 36532015, 2022). "AEBP1 and KLF2 were higher expressed, while DLX6, HOXB6, and RORB were lower expressed in endometriosis in the GSE7305 dataset." (PMID 36532015, 2022). "Using other machine learning approaches, both KLF2 and HOXB6 repeatedly appeared in Support Vector Machine Recursive Feature Elimination (SVM-RFE) and random forest models, implying their crucial role in endometriosis." (PMID 36532015, 2022). "A study focused on GSE51981, containing four stages of endometriosis and normal endometrium, pointed that the mRNA levels of AEBP1 and HOXB6 shifted in I/II, III/IV stages." (PMID 36532015, 2022). "Then, two of four TFs (KLF2, HOXB6) repeat occurrence in the following multiple modules (String, WGCNA), implying dominant contribution to endometriosis." (PMID 36532015, 2022). "AEBP1 and HOXB6, together with IGF-1, CYP11A1, MMP-2, CC2D2A, IER3, STX18, maybe staging markers for endometriosis." (PMID 36532015, 2022). "Our analyses point to, HOXB6, KLF2, and RORB, maybe cross-regulatory genes in endometriosis and SLE." (PMID 36532015, 2022). "NEAT1 and XIST may regulate the expression of four TFs (AEBP1, HOXB6, RORB, and KLF2) through the lncRNA-miRNA-mRNA network and participate in the development of endometriosis." (PMID 36532015, 2022). "Thus, HOXB6 and KLF2 were stable and valuable biomarkers across various models for endometriosis." (PMID 36532015, 2022). "AEBP1, HOXB6, KLF2, and RORB may be potential biomarkers for endometriosis." (PMID 36532015, 2022).
Huntington disease (1 paper, 2021). Huntington disease (HD) is a rare neurodegenerative disorder of the central nervous system characterized by unwanted choreatic movements, behavioral and psychiatric disturbances and dementia. "The hypermethylation in the HOXB gene cluster and HOXB6 gene were previously reported in brain and blood, respectively; in contrast, expression of HOXB9 was reported to be increased in the brain tissue from patients with Huntington disease." (PMID 34654479, 2021).
liver cancer (1 paper, 2020). An epithelial or non-epithelial malignant neoplasm that arises from the liver. "In addition, we overexpressed miR-126 or/and HOXB6 in liver cancer cell lines, respectively, and we found that overexpression of HOXB6 abrogated miR-126-induced increases in stem cell-related gene SOX9 expression." (PMID 32763157, 2020).
lung adenocarcinoma (1 paper, 2025). A carcinoma that arises from the lung and is characterized by the presence of malignant glandular epithelial cells. "Changes in immune evasion properties were also observed in a lung adenocarcinoma cell line upon reduction of HOXB6 and HOXB8 expression." (PMID 40619489, 2025). "In this study, we have focused on analyzing HOXB6 and HOXB8’s effects on pancreatic (and lung) adenocarcinoma in vitro, we also used publically available data from a larger collection of tumor samples to verify gene expression, immune cell infiltration, and correlate to patient outcomes." (PMID 40619489, 2025). "This suggests that HOXB6 and HOXB8 expression (in at least pancreatic and lung adenocarcinoma) enhance immunosuppressive effects of cancer cells by promoting immune evasiveness of macrophages and thereby contributing to an immunosuppressive microenvironment affecting macrophage differentiation." (PMID 40619489, 2025).
meningioma (1 paper, 2013). A generally slow growing tumor attached to the dura mater. "Homeobox protein Hox-B3 (HOXB3), LIM domain only protein 3 (LMO3), Homeobox protein Hox-B6 (HOXB6), Homeobox protein Hox-A3 (HOXA3) and DNA-binding protein inhibitor ID-2 (ID2) showed higher under-expression in benignB with respect benignA meningiomas with a fold change lower than −3." (PMID 23840654, 2013).
microtia (1 paper, 2025). "We initially confirmed the association between HOXB6 expression and microtia." (PMID 39897132, 2025). "The binding of HOXB6 to enhancer regions of these genes directly influences their expression, providing valuable insights into the molecular basis of microtia pathogenesis." (PMID 39897132, 2025). "This study validates the down-regulation of HOXB6 in auricle cartilage obtained from microtia patients." (PMID 39897132, 2025). "However, the specific role of HOXB6 in microtia remains elusive." (PMID 39897132, 2025).
migraine (1 paper, 2021). "For instance, we identified a new region associated with migraine at 17q21 and our DEPICT gene analysis prioritized three members of the Antp homeobox family genes (i.e., HOXB2, HOXB3, and HOXB6) at this region that encode proteins with a homeobox DNA-binding domain." (PMID 34294844, 2021).
myeloma (1 paper, 2024). "SERPINE1 (together with ANGPTL4, GDF15, CXCL12, SOX9, HOXB6, and ANK3) was even described as a TA-MSC factor, namely, in mesenchymal stromal cells of the bone marrow that supported myeloma cell growth." (PMID 39011489, 2024).
ovarian carcinoma (1 paper, 2012). A malignant neoplasm originating from the surface ovarian epithelium. "For example, Module 37 includes four HOX family genes (HOXB2, HOXB4, HOXB6 and HOXB7) that all have been extensively reported to be related with ovarian cancer." (PMID 22863767, 2012).
ovarian tumors (1 paper, 2022). "HOXB6 has been reported to be associated with the occurrence of ovarian tumors." (PMID 36452142, 2022).
pancreatic cancer (1 paper, 2025). "Loss of function experiments in pancreatic cancer cell lines demonstrated that HOXB6 and HOXB8 control cancer cell proliferation, viability, apoptosis, senescence, and sensitivity to gemcitabine." (PMID 40619489, 2025). "Loss of HOXB6 and HOXB8 in pancreatic cancer cells inhibited cell proliferation, induced apoptosis and senescence and enhanced gemcitabine sensitivity." (PMID 40619489, 2025). "To determine if these observations were functionally relevant in PDAC cells, we knocked down (KD) HOXB6 and/or HOXB8 expression using siRNAs (i.e., siHOXB6, siHOXB8, and siHOXB6B8) in the human pancreatic cancer cell lines PANC-1 and AsPC1." (PMID 40619489, 2025). "In this study, we define the role of homeobox protein B6 (HOXB6) and HOXB8 in controlling pancreatic cancer tumorigenesis and immune response." (PMID 40619489, 2025). "Most importantly, we show that HOXB6 and HOXB8 KD impaired tumor cell proliferation, differentiation, and maintenance further supporting that HOXB6 and HOXB8 are important regulators of pancreatic cancer stem cells." (PMID 40619489, 2025). "However, to establish a critical role for HOXB6 and HOXB8 in pancreatic cancer biology, animal models and primary human PDAC cell culture will be needed to verify our findings in an in vivo setting." (PMID 40619489, 2025). "Our findings indicate that HOXB6 and HOXB8 play important roles in regulating cell proliferation, immune response, and treatment resistance to promote pancreatic cancer tumorigenesis and could be useful therapeutic targets." (PMID 40619489, 2025). "Interestingly, HOXB6 and HOXB8 bind to and activate expression of one another and other HOX genes expressed in pancreatic cancer cells suggesting that a HOX transcriptional network is active in PDAC similarly to what has been described in other solid tumors." (PMID 40619489, 2025).
serous ovarian tumor (1 paper, 2021). "First, we measured the expression of the uterine-associated transcription factor HOXB6, and the UCEC serous ovarian tumor biomarker WT1 in SK-OV-3, in the OV cell line Caov-4, and in the UCEC cell line HEC-59." (PMID 33926541, 2021).
cancer (9 papers, 2018 to 2025). A tumor composed of atypical neoplastic, often pleomorphic cells that invade other tissues. "To determine if HOXB6 and/or HOXB8 regulate the immune response specifically in PDAC, we performed a TIMER association analysis of HOXB6 and HOXB8 expression with all TCGA cancer samples currently included in this analysis module." (PMID 40619489, 2025). "RNA-seq and ChIP-seq analyses showed that HOXB6 and HOXB8 directly regulate expression of genes critical for cell proliferation (HOXB6) and immune-cancer cell interaction (HOXB6 and HOXB8)." (PMID 40619489, 2025). "Studies have shown that the HOXB gene cluster contributes to cancer development; increased expression of HOXB3, HOXB6, HOXB7, HOXB8, and HOXB9 in LUAD patients is linked with poor overall survival (OS)." (PMID 36506331, 2022). "The downregulation of HOXA5 increased the expression of HOXB6 and HOXB7, which were associated with poor clinical outcomes in cancer patients." (PMID 35054365, 2022). "From the 40 cancer types studied, HOXB6 and HOXB8 expression correlated with cancer-associated fibroblast and myeloid-derived suppressor cell infiltration in 7 different types of cancer." (PMID 40619489, 2025). "Since SOX9+/HNF4α+ HybHPs was regenerated in the injured liver without developing into cancer, we focused on the Hoxb6 effects on the HybHPs." (PMID 32763157, 2020). "For example, tumor cell behavior (proliferation, apoptosis, senescence) in response to reduced HOXB6 and HOXB8 expression could be observed and co-culture experiments with M0 macrophages allowed us to study if HOXB6 and HOXB8 are important for immune-cancer cell interactions." (PMID 40619489, 2025). "The results showed that some HOX genes in pan-cancer had significant strong correlation (R≥0.8): HOXA9 with HOXA10, HOXB5 with HOXB6 and HOXB8, HOXB8 with HOXB6 and HOXB9, HOXB3 with HOXB4 and HOXB5 and HOXB6, HOXC8 with HOXC9, HOXC9 with HOXC10, HOXD10 with HOXD11." (PMID 39980564, 2025).
tumor (6 papers, 2021 to 2025). "Co-culture of HOXB6 and HOXB8 deficient PDAC cells with macrophages confirmed that HOXB6 and HOXB8 promoted tumorigenic properties of tumor-associated macrophages and protected PDAC cells from macrophage detection." (PMID 40619489, 2025). "A previous transcriptional characterization of PDAC stem cells showed that these cells have abundant HOXB6 expression suggesting that HOXB6 function promotes tumor stem cells." (PMID 40619489, 2025). "First, we examined if reduced HOXB6 and HOXB8 expression affected clonogenic capacity of tumor cells by performing colony formation assays." (PMID 40619489, 2025). "HOXB6 correlated with BMI1 and SOX9 expression levels and previous studies have shown that SOX9 enhances tumor progression through BMI1 binding and p21 down-regulation which induces cell proliferation and evasion of apoptosis and senescence." (PMID 40619489, 2025). "This analysis underscores the precise involvement of HOXB6, HLA-F, and CAMKV in tumor progression through T cell activation processes in the luminal A subtype." (PMID 38012271, 2023). "Comparing benign to tumour samples, HOXA6 (p = 4.26 × 10−5), HOXB6 (p = 0.001), HOXC5 (p = 4.69 × 10−5), HOXC6 (p = 3.02 × 10−28), and HOXC9 (p = 0.0001) all showed significantly greater expression in tumour samples, with HOXC6 having by far the greater fold difference." (PMID 40725480, 2025).
adenocarcinoma (1 paper, 2025). A common cancer characterized by the presence of malignant glandular cells. "Our data suggest that HOXB6 and HOXB8 regulate numerous oncogenic pathways to promote adenocarcinoma tumorigenesis." (PMID 40619489, 2025).
HOXB6 also shares sentences with these, for which no sentence is quoted: amyotrophic lateral sclerosis (1 paper); celiac disease (1); colon adenocarcinoma (1); epilepsy (1); Hutchinson-Gilford progeria (1); infertile (1); liver diseases (1); mammary tumours (1); pancreatic (1); small cell carcinoma (1).